COMT (catechol-O-methyltransferase)
Diseases named in the same sentence as COMT in open-access papers (continued):
Sharing a sentence is not in itself a finding about the gene and the disease.
fibromyalgia (continued). "Our data seem to agree with such data suggesting that patients with fibromyalgia carrying the Met allele of the COMT gene would show a great severity of the syndrome, being especially sensitive to the influence of affective variables (i.e., fear of pain) on self-reported fatigue." (PMID 33909692, 2021). "Therefore, the aim of the present case-control study was to examine differences in pain and fatigue, as well as several other psychological outcomes, in patients with fibromyalgia associated with the COMT gene." (PMID 33909692, 2021). "Likewise, COMT polymorphisms, specifically the Val158Met polymorphism, have also been related to psychological symptomatology in fibromyalgia." (PMID 33909692, 2021). "Experimental evidence has suggested that fibromyalgia patients carrying the two Met alleles of the COMT gene had a higher number of tender points, greater sensibility to painful stimulation and, also, a higher severity of depressive and anxious symptomatology than Val carriers." (PMID 32752289, 2020). "Specific genotypic variations of the COMT gene (i.e., Val/Val allele carriers) might contribute to diminished cognitive performance in fibromyalgia, mainly in visuo-spatial working memory tasks." (PMID 32752289, 2020). "Therefore, we evaluated the association of fibromyalgia with a multi-SNP haplotype, evidenced to be more predictive of COMT enzymatic activity, and associated with a > 20-fold difference." (PMID 30886988, 2018). "A case control study involving 61 Turkish fibromyalgia patients has previously reported a higher frequency of Val/Met heterozygotes and also an association between individuals heterozygous for COMT gene polymorphisms rs464312 and rs6269 and pain sensitivity has previously been reported." (PMID 22612913, 2012). "Indeed, patients with fibromyalgia carrying the methionine allele and with higher scores of medical fear of pain reported a more intense feeling of fatigue than patients carrying the Val/Val genotype of the COMT gene." (PMID 33909692, 2021). "Thus, the present research is the first to report that different levels of fear of pain may act as a moderating factor in the relationship between the Met allele of the COMT gene and self-reported fatigue in fibromyalgia." (PMID 33909692, 2021). "However, some authors have found a relationship between the Met allele of COMT (i.e., lower COMT activity) and the risk of suffering from chronic fatigue syndrome, a disease that shares some aetiological mechanisms with fibromyalgia." (PMID 33909692, 2021). "Specifically, post-hoc analyses revealed that patients with fibromyalgia carrying the Val/Val genotype showed greater P2 frontocentral amplitudes than healthy control participants carrying the same COMT genotype (p = 0.001)." (PMID 36100778, 2023). "COMT regulates nociceptive processing and inflammation, key pathophysiological features of Chronic Fatigue Syndrome and Fibromyalgia (CFS/FM)." (PMID 36284330, 2022). "Two types of statistical analyses were performed; the first was undertaken to explore the influences of COMT genotypes on clinical symptoms by comparing patients with fibromyalgia and healthy controls." (PMID 33909692, 2021). "The lack of available empirical evidence linking self-reported fatigue and COMT genotypes in fibromyalgia makes it difficult to provide a straightforward explanation of these findings." (PMID 33909692, 2021). "Thus, the present research suggests that fear of pain, as a psychological symptom frequently described in fibromyalgia may act as a moderating factor in the relationship between the Met allele of the COMT gene and the increase or decrease in self-reported fatigue." (PMID 33909692, 2021). "The present investigation aimed to explore the relationship between the different genotypes of the COMT gene and working memory dysfunction in fibromyalgia." (PMID 32752289, 2020).
fibromyalgia (continued). "The frequency of the COMT rs4680 polymorphism distribution fulfilled the HWE in both the HC participants (χ2 = 0.351, p = 0.553) and fibromyalgia patients (χ2 = 0.04, p = 0.825)." (PMID 32752289, 2020). "The COMT gene has been widely studied with respect to the pain-related and affective symptoms of chronic pain syndromes, such as fibromyalgia." (PMID 32752289, 2020). "In summary, this investigation aimed to explore the relationship between the different genotypes of COMT and working memory dysfunction in fibromyalgia." (PMID 32752289, 2020). "In summary, our data are the first to establish a role of COMT, a gene involved in the availability of dopamine, on working memory dysfunction in fibromyalgia patients." (PMID 32752289, 2020). "Our findings are the first to show a link between the COMT gene and working memory dysfunction in fibromyalgia, supporting the idea that higher COMT enzyme activity would contribute to more severe working memory impairment in fibromyalgia." (PMID 32752289, 2020). "To this end, we analysed the rs4680 SNP of the COMT gene in fibromyalgia patients and healthy participants and measured their performance in neuropsychological tests involving working memory processing." (PMID 32752289, 2020). "This fact, together with the generalized compensatory processing here detected in fibromyalgia, could contribute to explain the enhancement of neural indices (frontocental P2 amplitudes) in patients carrying Val/Val genotype of the COMT gene." (PMID 36100778, 2023). "In the present research we applied a spatial n-back paradigm to explore how distinct indices of working memory capacity (ERPs and behavior) might be modulated by different genotypes of the COMT gene in patients with fibromyalgia." (PMID 36100778, 2023). "Therefore, the aim of the present research was to investigate the potential effect of the COMT gene in fibromyalgia patients on ERP working memory indices (P2 and P3 components)." (PMID 36100778, 2023). "Interestingly, we also observed that only fibromyalgia patients carrying the Val/Val genotype of the COMT gene showed higher frontocentral P2 amplitudes than control participants (p < 0.05)." (PMID 36100778, 2023). "These promising data could help to better characterize working memory impairment in fibromyalgia, considering Val/Val genotype of the COMT gene as a biological marker useful to generate different patient profiles." (PMID 36100778, 2023). "More interestingly, we will explore how different affective and cognitive symptoms might moderate the relationship between specific genotypes of the COMT gene and self-reported fatigue and pain in patients with fibromyalgia." (PMID 33909692, 2021). "This accumulated evidence leads us to suggest that COMT, as a genetic marker involved in dopamine availability, might be a useful target to better characterise cognitive dysfunction in fibromyalgia." (PMID 32752289, 2020). "Although these data should be confirmed in future studies, our results suggest that the enzymatic activity of COMT might modulate the cognitive performance of fibromyalgia patients, mainly in spatial working memory tasks." (PMID 32752289, 2020). "Specifically, fibromyalgia patients carrying the Val/Val genotype (i.e., having high COMT activity leading to higher dopamine degradation) exhibited significantly worse performance in terms of the span of SST backward, SST backward score, SST total score and Working Memory Index of the WMS-III." (PMID 32752289, 2020). "Common COMT haplotypes were not specifically associated with FM either, suggesting that COMT enzymatic activity and catecholamine levels, per se, are not driving the development of fibromyalgia pain." (PMID 30886988, 2018). "For example a low COMT activity has been associated with chronic facial pain, fibromyalgia and women with non-migrainous headache." (PMID 21437260, 2011).
fibromyalgia (continued). "Thus, it could be thought that the influence of the COMT gene on the amplitude of the frontocentral P2 may be characterizing working memory dysfunction in fibromyalgia." (PMID 36100778, 2023). "Thus, both the increase in cytokines and the reduction in endogenous opioid receptors could be considered plausible explanations to support the role played by COMT (Met/Met genotype) in the severity of fatigue symptoms in fibromyalgia." (PMID 33909692, 2021). "However, despite the frequently reported relationship between working memory impairment and fibromyalgia, the effect of biological indices (i.e., the COMT gene) related to dopamine availability on cognitive resources in these patients has not been explored to date." (PMID 32752289, 2020). "Results of the multiple regression analysis for the interaction term (COMT x FPQ-III medical) for fatigue and pain equation in individuals with fibromyalgia." (PMID 33909692, 2021). "Catechol-O-methyltransferase (COMT), the most widely studied gene in fibromyalgia, is involved in degrading catecholamines and several other neurotransmitters and, therefore, in modulating pain perception by the CNS." (PMID 29486785, 2018). "Unlike some prior investigations, we found no clear mediating role of the COMT gene (fibromyalgia patients carrying Val/Val genotype) on P3 amplitudes." (PMID 36100778, 2023). "Despite the extensive amount of scientific evidence about the symptomatology of fibromyalgia, fatigue has not been explored in relation to the COMT gene in this syndrome." (PMID 33909692, 2021). "ANCOVAs revealed that the influence of the COMT genotypes on clinical outcomes was independent of age (for both patients with fibromyalgia and HC participants)." (PMID 33909692, 2021).
migraine (19 papers, 2009 to 2026). "Our study, reasonably, cuts out a direct involvement of COMT gene polymorphisms in migraine even when considering the rs4818 polymorphism." (PMID 25929431, 2015). "In this study, for the first time, we focused on the role of COMT rs4818 genetic variant, the polymorphism most strongly affecting COMT activity, in migraine." (PMID 25929431, 2015). "In a meta-analysis of all studies concerning COMT rs4680 and risk of migraine, carriers of the AA genotype versus carriers of GG + GA genotypes had 24% decreased migraine risk (AA vs. GG + GA: OR = 0.76, 95% CI = 0.60–0.97, PHet > 0.642, I2 = 0)." (PMID 26632697, 2015). "COMT polymorphisms associated with lower COMT activity have been studied in several painful conditions, such as postoperative surgery, cancer pain, neuropathic pain, and migraine or headache, not only in adult subjects but also in paediatric populations." (PMID 30704436, 2019). "In addition, the study in Finns by Tammimaki and Mannisto42 demonstrated some evidence for an increase in the migraine risk associated with COMT rs4680 polymorphism." (PMID 26632697, 2015). "However, COMT rs4680 polymorphism was associated with a decreased risk of migraine, especially in Caucasians." (PMID 26632697, 2015). "Moreover, our replication study supports previous results excluding any correlation between COMT rs4680 polymorphism and migraine in Caucasians patients, in contrast with a putative correlation found only in Korean and Turkish population." (PMID 25929431, 2015). "The study of COMT gene polymorphisms in migraine could be of particular interest since impaired catecholaminergic neurotransmission, namely chronic dopaminergic and noradrenergic hypofunction, is a peculiar migraine trait." (PMID 25929431, 2015). "This is the first COMT study performed on a cohort of carefully clinical characterized Caucasian migraineurs recruited in a specifically dedicated migraine biobank and focused on the role of rs4818 variant, the polymorphism most strongly affecting COMT activity." (PMID 25929431, 2015). "Of the 25 overlapping genes/loci, 6 genes/loci were associated with more than 2 phenotypes in HPGDB (COMT, OPRD1, IL1A, IL1B, TSPAN2/NGF, GDF5), and 15 genes were associated with migraine." (PMID 37144689, 2023). "Taken together, two key differentially expressed metabolites (DOPAC and HPP), two key targets (MAO-A and COMT), and one relevant metabolic pathway (tyrosine metabolism) showed great importance in the treatment of migraine." (PMID 35401159, 2022). "Further experiments demonstrated that the contents of MAO-A and COMT were significantly increased in serum and brainstem tissue of the migraine rats." (PMID 35401159, 2022). "Compared with the control rats, the contents of MAO-A and COMT were significantly increased in the migraine rats." (PMID 35401159, 2022). "Accordingly, it can be supposed that two key differentially expressed metabolites (DOPAC and HPP), two key targets (MAO-A and COMT), and one key metabolic pathway (tyrosine metabolism) were closely involved in the treatment of migraine by CRCR extract." (PMID 35401159, 2022). "MAO-A and COMT, the key enzymes involved in the tyrosine metabolism, were also significantly increased in the migraine rats." (PMID 35401159, 2022). "Some epidemiological studies have investigated the relationship between genetic polymorphisms of DRD2, COMT, DBH, and MAO-A and migraine susceptibility, but the results are still inconsistent." (PMID 26632697, 2015). "Multiple epidemiological studies have investigated the association between migraine susceptibility and polymorphisms of the four genes DRD2, COMT, DBH, and MAO-A." (PMID 26632697, 2015). "However, COMT rs4680 polymorphism may decrease the risk of migraine, especially in Caucasians." (PMID 26632697, 2015). "Variability in the COMT gene was associated with migraine, but the two remaining genes did not relate to migraine." (PMID 31739474, 2019).
migraine (continued). "The association between five COMT polymorphisms and migraine with or without aura and tension-type headache was studied in a Japanese sample population." (PMID 29890676, 2018). "In conclusion, COMT genotype does not influence migraine susceptibility or phenotype, even when considering peculiar clinical subtypes (dopaminergic migraine, HMM)." (PMID 25929431, 2015). "COMT genotype does not influence migraine susceptibility or phenotype, even considering rs4818 polymorphism and peculiar clinical subtypes." (PMID 25929431, 2015). "A larger study of epigenetic changes in SH2D5, NPTX2, COMT, GIT2, ZNF234, and SOCS1 genes is necessary to understand the processes of migraine chronicity and MOH development." (PMID 37298078, 2023). "The integrated analysis revealed that two key differentially expressed metabolites (DOPAC and HPP), two key targets (MAO-A and COMT), and one relevant metabolic pathway (tyrosine metabolism) showed great importance in CRCR treating migraine." (PMID 35401159, 2022). "Genotyping of rs4680 and rs4818 Catechol-O-Methyltransferase gene polymorphisms was performed on 380 unrelated migraine patients, and 132 healthy subjects matched for age, gender and race-ethnicity, with no clinical evidence or family history of migraine or other neurological diseases." (PMID 25929431, 2015). "One study showed that methylation of some CpG sites of COMT, GIT2, ZNF234, and SOCS1 genes could be important for drug addiction and transformation of migraine into MOH, but studies on larger patient cohorts are needed to fully explore this issue." (PMID 37298078, 2023).
Obesity (19 papers, 2009 to 2026). Accumulation of substantial excess body fat. "Changes in the COMT activity, associated with genetic variants in the COMT gene have consequences in various mechanisms connected with development of obesity, personality changes and behavior disturbances." (PMID 29225702, 2017). "Folate status is inversely associated with obesity, likely due to increased activity of COMT (catechol O-methyltransferase), which uses folate for methyl transfer for metabolism of catechol estrogen produced by adipose tissue." (PMID 23656756, 2013). "Several studies have found modest associations between obesity and the rs4680 (Val158Met) SNP of COMT." (PMID 21304959, 2011). "Several polymorphisms of COMT have been described, but 24938A/G (rs4680) is the most extensively studied showing associations with schizophrenia, alcoholism and obesity." (PMID 19690620, 2009). "Based on the present findings on glucose homeostasis, IGT and T2D for 5HT2C and COMT, we examined the combined genotype association of the minor risk genotypes of 5HT2C and COMT in relation to obesity and related metabolic traits." (PMID 19690620, 2009). "A case study in 2015 validated that the polymorphisms of COMT may be correlated with obesity occurrence." (PMID 29258237, 2017). "Odds ratio (OR) including 95% confidence intervals (CI) for 5HT2A rs6311 (dominant effect of the A allele, AA & AG vs GG), 5HT2C rs3813929 (effect of the T vs C alleles) and COMT rs4680 (recessive effect of the G allele, GG vs GA & AA) in relation to obesity phenotypes." (PMID 19690620, 2009). "Another promising target for obesity intervention is the enzyme catechol-O-methyltransferase (COMT), which deactivates norepinephrine (NE) by methylation." (PMID 41009815, 2025). "The COMT gene was found to be significantly related to hypertension, dyslipidemia, insulin resistance, obesity, and drug abuse." (PMID 38254998, 2024). "The COMT gene was found to be significantly related to hypertension, dyslipidemia, insulin resistance, obesity, and drug abuse, with rs4680 being the most commonly reported variant." (PMID 38254998, 2024). "COMT (ENSP00000354511) has also been predicted to be a co-related gene for both obesity and psychiatric diseases." (PMID 29258237, 2017). "COMT has been studied intensively in relation to several reward-motivated behaviours such as development of diet-induced obesity." (PMID 19690620, 2009). "In the present study, we examined 5HT2A –1438G/A (rs6311), 5HT2C -759C/T (rs3813929) and COMT 24938 A/G (rs4680) in relation to obesity and related metabolic quantitative traits in a group of middle-aged men representing a very broad range of BMI." (PMID 19690620, 2009). "We identified 3 genes at 22q11.2 (TBX1, COMT and MAPK1) that could confer susceptibility to obesity." (PMID 29441128, 2018). "Moreover, COMT has been shown to be involved in reward-motivated behaviors such as development of diet-induced obesity through metabolizing dopamine." (PMID 22715380, 2012). "The present study revealed that the examined SNPs of 5HT2A and 5HT2C did not associate with obesity, but COMT 24938A/G was associated with fat-BMI." (PMID 19690620, 2009). "Moreover, obesity in pregnant patients increases the odds of antenatal and postpartum depression through a complex genetic crosstalk between polymorphisms of serotonin (HTR2A), catecholamine (COMT and MAOA), HPA-axis (CRHR1), and oestrogen receptor genes." (PMID 41375608, 2025). "Moreover, a study has suggested that catechol-O-methyltransferase may participate in the development of obesity." (PMID 34650609, 2021). "However, our results also implied that the combined genotypes of 5HT2C –759C/T and COMT 29438A/G may have an impact on obesity and thus, in this way, on the development of IGT or T2D." (PMID 19690620, 2009).
Obesity (continued). "There is evidence that changes in the activity of COMT affect sympathetic tone, regulate the amounts of active dopamine and noradrenaline in various cerebral regions and thus is involved in multiple reward-motivated behaviour such as obesity, mood and other mental processes." (PMID 19690620, 2009). "Although the exact mechanisms for this relationship are not clear, reduced catechol-O-methyltransferase (COMT) activity associated with obesity and/or suppressed COMT activity by estradiol may explain the decreased methylation of catechols with increased BMI observed in the present study." (PMID 28284224, 2017). "At first step, our results suggested that 5HT2C –759C/T and COMT 29438A/G is associated with IGT and T2D, but partly independent of obesity." (PMID 19690620, 2009). "One study investigating MAOA and COMT genotypes in obese subjects compared to controls found no significant relation between the MAOA genotype and obesity." (PMID 37893019, 2023).